SIRT2 (sirtuin 2)
Diseases named in the same sentence as SIRT2 in open-access papers (continued):
Sharing a sentence is not in itself a finding about the gene and the disease.
neuropathy (5 papers, 2020 to 2025). A disorder affecting the nervous system that manifests with pain, tingling, numbness, and/or muscle weakness. "We have previously provided genetic evidence that the NAD+-dependent deacetylase, SIRT2, protects against cisplatin-induced peripheral neuronal cell death and neuropathy by enhancing nucleotide excision repair." (PMID 35875690, 2022). "Our findings demonstrate the pathogenic role of SIRT2‐dependent α‐tubulin deacetylation in mutant GARS‐induced neuropathies and provide new perspectives for targeting SIRT2 as a potential therapy against hereditary axonopathies." (PMID 34053152, 2021). "Our findings demonstrate the pathogenic role of SIRT2‐dependent α‐tubulin deacetylation in mutant GARS‐induced neuropathies and provide new possibilities for targeting SIRT2 as a potential therapy against hereditary axonopathies." (PMID 34053152, 2021). "Much evidence suggests that Sirt2 protects tissues from injury, including neuropathy resulting from various insults." (PMID 32122297, 2020). "By our laboratory and others, the overexpression of Sirt2 can improve cisplatin-induced neuropathy, although the mechanism is still unclear." (PMID 32122297, 2020). "While there is a substantial amount of literature indicating a protective role for Sirt2 in cisplatin-induced neuropathy, the mechanism by which Sirt2 protects against cisplatin-induced neuropathy is unknown." (PMID 32122297, 2020). "Sirt2 may be a potential target for the prevention and treatment of chemotherapy-induced neuropathy." (PMID 32122297, 2020). "The underlying mechanism by which Sirt2 protects neurons from cisplatin-induced neuropathy is not clearly understood." (PMID 32122297, 2020). "In addition, Sirt2 could potentially serve as a target in the treatment and prevention of cisplatin-induced neuropathy." (PMID 32122297, 2020). "One hypothesis is that Sirt2 regulation of cisplatin-induced neuropathy is immune mediated." (PMID 32122297, 2020). "In the present proteomics samples, the serum SIRT2 levels were higher in patients who developed neuropathic pain compared with those who had neuropathy without pain." (PMID 35408848, 2022). "Circulating SIRT2 levels could also have been influenced by unmeasured confounders, including medication use, dietary factors, and the presence of other diabetic complications such as retinopathy or neuropathy, which were not systematically evaluated." (PMID 41303131, 2025). "Since SIRT2 is most abundant in skeletal muscle and the aging central nervous system, we hypothesis these GARS mutants lose the binding with SIRT2 and result in a significant decrease in the acetylated tubulin in muscle and CNS, which might contribute the neuropathy like CMT." (PMID 34053152, 2021).
steatosis (5 papers, 2021 to 2023). Increased lipid within the cytoplasm of cells. "Accordingly, our study shows that SIRT2 ablation is sufficient to induce steatosis on a regular diet, which was exacerbated with the consumption of a HFD." (PMID 35743232, 2022). "We next used Oil Red O (ORO) staining to assess hepatic neutral lipid accumulation and found that HFD-fed SIRT2-KO mice show increased lipid accumulation (steatosis) compared to WT mice." (PMID 35743232, 2022). "The hepatic tissues presented different degrees of immunoreactive scores (IRS) of SIRT2, steatosis, and liver damage." (PMID 34642310, 2021). "Although the beneficial effects of caloric restriction are largely attributed to SIRT1 activation, resveratrol can modulate the activity of other sirtuins, making it possible that SIRT2 activation may improve steatosis through an ER stress-dependent pathway." (PMID 35743232, 2022). "This is relevant to our observed low SIRT2 expressions in in vivo and in vitro steatosis, which were upregulated by AICAR independent of AMPK." (PMID 36834782, 2023).
allergic asthma (4 papers, 2022 to 2025). A asthma with a basis in a pathological type I hypersensitivity reaction. "For example, SIRT2 aggravates allergic asthmatic inflammation, where inhibiting SIRT2 pharmacologically alleviates its severity, whereas genetic overexpression of SIRT2 worsens the allergic asthma phenotype." (PMID 41008562, 2025). "For instance, accumulating studies have shown that SIRT2 exacerbates airway inflammation in allergic asthma." (PMID 38041162, 2023). "Accumulating studies indicate that SIRT2 can activate ER stress response, and it mediates the exacerbation of allergic asthma." (PMID 38041162, 2023). "SIRT2 is shown to be a contributor of airway inflammation in allergic asthma." (PMID 38041162, 2023). "Other data suggest that after allergen sensitization and excitation, overexpression or inhibition of SIRT2 modulates the expression of CCL17 and the recruitment of monocytes and macrophages into the airways, so SIRT2 enhances allergic asthma inflammation." (PMID 35620467, 2022).
Anxiety (4 papers, 2015 to 2024). Intense feelings of nervousness, tension, or panic often arise in response to interpersonal stresses. "Further experiments in older animals with increased anxiety are needed to evaluate the potential anxiolytic properties of SIRT2 inhibition as has been suggested previously." (PMID 37698780, 2023). "Analysis of behavior in the elevated plus test showed lower indices of anxiety in Ad-SIRT2-GFP rats than in controls: Ad-SIRT2-GFP rats displayed more entries, spent more time in the open arms, and moved more in all areas of the elevated plus maze." (PMID 25672834, 2015). "HDAC6 has demonstrated a key role in mood and anxiety via a-tubulin regulation within serotonergic neurons of the dorsal raphe nucleus but the interaction with SIRT2 ties this more closely to cellular energy levels due to SIRT2’s dependence on NAD+." (PMID 39404407, 2024).
diabetic nephropathy (4 papers, 2022 to 2025). "Multinomial logistic regression analysis, visualized with a forest plot, confirmed SIRT2’s independent association with diabetic nephropathy, adjusting for factors like age, sex, BMI, glycemic indices, lipid profile, blood pressure, and renal function." (PMID 41303131, 2025). "Collectively, these results position SIRT2 as a novel, independent biomarker that is complementary to traditional metabolic risk factors and support its potential role in risk stratification of diabetic nephropathy." (PMID 41303131, 2025). "Combined with the findings of the present study, this suggests that SIRT2 may act as a pathogenic factor in diabetic nephropathy and contribute to the progression of the disease." (PMID 35493297, 2022). "This dichotomy underscores the biological complexity of SIRT2 and emphasizes the importance of defining its role specifically within diabetic kidney disease." (PMID 41303131, 2025). "In conclusion, this study demonstrates that circulating SIRT2 is markedly elevated in patients with diabetic nephropathy, including those at the microalbuminuric stage, and remains independently associated with the disease beyond established risk factors." (PMID 41303131, 2025). "Taken together, these clinical and preclinical observations implicate SIRT2 in pathways relevant to diabetic kidney disease, supporting its potential as a nephropathy-related biomarker that complements, rather than replaces, conventional indices." (PMID 41303131, 2025). "This study aimed to assess the relationship between serum SIRT2 levels and the presence of diabetic nephropathy and to evaluate its potential utility as a complementary biomarker reflecting early renal injury." (PMID 41303131, 2025). "In contrast to the other SIRTs that have a renoprotective effect, Sirt2 has been shown to promote kidney injury, induced by chemical compounds, and diabetic nephropathy by decreasing cellular autophagy and increasing apoptosis and inflammation." (PMID 39907422, 2025). "The effect of SIRT2 on diabetic nephropathy has been less studied clinically." (PMID 36139886, 2022). "The stepwise increase observed across study groups, supported by experimental and proteomic findings, suggests that SIRT2 may represent a promising biomarker and could be involved in potentially modifiable pathophysiological pathways in diabetic kidney disease." (PMID 41303131, 2025). "However, the effect of SIRT2 on diabetic nephropathy has been less studied clinically." (PMID 35493297, 2022).
frontotemporal dementia (4 papers, 2014 to 2023). Frontotemporal dementia (FTD) comprises a group of neurodegenerative disorders, characterized by progressive changes in behavior, executive dysfunction and language impairment, as a result of degeneration of the medial prefrontal and frontoinsular cortices. "Still, our data are consistent with findings in a mouse model of frontotemporal dementia, where specific inhibition of SIRT2 by AK-1 in the hippocampus revealed a neuroprotective effect and prevented neuronal loss in this area." (PMID 36719240, 2023). "AK-1, a small molecule SIRT2 inhibitor, shows neuroprotective effects in a mouse model of frontotemporal dementia (FTD) by regulating the expression of mutant tau protein." (PMID 37215138, 2023).
gastric tumors (4 papers, 2017 to 2025). "Combining elesclomol with AGK2, a SIRT2-specific inhibitor, induce cuproptosis in gastric tumors in vitro and in vivo." (PMID 37863889, 2023). "Therefore more studies are necessary to determine the exact function of SIRT2 in gastric tumor progression." (PMID 28061480, 2017).
Hyperglycemia (4 papers, 2018 to 2025). An increased concentration of glucose in the blood. "Having identified β cell states associated with hyperglycemia, we asked whether SIRT2 inactivation affects glucose-induced β cell state transitions by analyzing islets from Sirt2Δβ mice treated with S961." (PMID 40762838, 2025). "As Sirt2 deletion prevented most β cells from transitioning to the more stressed β-5 state in response to S961 treatment, these observations suggest that hyperglycemia activated a stress response in β cells in a SIRT2-dependent manner." (PMID 40762838, 2025). "Sirt2 deletion in β cells of mice increased β cell proliferation during hyperglycemia with little effect under homeostatic conditions, indicating preservation of feedback control of β cell mass." (PMID 40762838, 2025). "At the transcriptomic level, Sirt2 inactivation has context-dependent effects on β cells, with Sirt2 controlling how β cells interpret hyperglycemia as a stress." (PMID 40762838, 2025). "Namely, Sirt2 deletion ameliorated signatures of the UPR and of the β cell exhaustive adaptive response during hyperglycemia, indicating that SIRT2 affects how β cells interpret hyperglycemia as a stress." (PMID 40762838, 2025). "As stressors such as ER stress can arrest β cell proliferation, we propose that SIRT2-dependent stress responses restrain β cell expansion during hyperglycemia, thereby linking SIRT2’s effect on β cell proliferation to chronically elevated glucose." (PMID 40762838, 2025). "Analysis of acetylated proteins in islets treated with a SIRT2 inhibitor revealed that SIRT2 deacetylates enzymes involved in oxidative phosphorylation, dampening the adaptive increase in oxygen consumption during hyperglycemia." (PMID 40762838, 2025). "In addition to its direct effect on metabolism, SIRT2 affects hyperglycemia-induced changes to β cell transcriptional states, providing a link between chronic elevations in glucose levels and SIRT2 function." (PMID 40762838, 2025). "Sirt2 deletion alters hyperglycemia-induced shifts in the β cell transcriptional state." (PMID 40762838, 2025). "Finally, we provide proof of principle that systemic administration of a glucagon-like peptide 1–coupled (GLP1-coupled), Sirt2-targeting antisense oligonucleotide achieves β cell Sirt2 inactivation and stimulates β cell proliferation during hyperglycemia." (PMID 40762838, 2025). "As we found that SIRT2 regulates β cell proliferation in a glucose-dependent manner ex vivo, we hypothesized that the effect of Sirt2 deletion on β cell proliferation in vivo would be contingent on hyperglycemia." (PMID 40762838, 2025). "The glucose dependence of SIRT2’s effect on β cell proliferation suggests that Sirt2 deletion could affect how β cells interpret hyperglycemia." (PMID 40762838, 2025). "Sirt2 deletion did not increase the relative β cell area compared with S961-treated control mice, possibly due to the short duration of hyperglycemia." (PMID 40762838, 2025). "If the hepatic levels of NAD+ and of keratin 8 and GKRP deacetylation reflect hepatic Sirt2 activity, it is plausible that a decrease in Sirt2 activity in the obese diabetic livers results in compromised regulation of HGU and glucokinase translocation by postprandial hyperglycemia." (PMID 29296001, 2018).
Hypertension (4 papers, 2014 to 2024). The presence of chronic increased pressure in the systemic arterial system. "In addition, Ang II and mechanical stretch stimulated microtubule redistribution and deacetylation via SIRT2 in ECs, suggesting the emerging role of SIRT2 in hypertension-induced vascular remodeling." (PMID 39281836, 2024).
nasopharyngeal carcinoma (4 papers, 2019 to 2021). A carcinoma arising from the nasopharyngeal epithelium. "Moreover, SIRT2 overexpression antagonizes the cytotoxicity of lapatinib in nasopharyngeal carcinoma." (PMID 34067290, 2021). "It was demonstrated that SIRT2 could antagonize the cytotoxicity of lapatinib in nasopharyngeal carcinoma." (PMID 33207824, 2020). "Similarly, SIRT2-mediated FOXO3 deacetylation has also been implicated in lapatinib response and sensitivity, and that SIRT2 can specifically antagonise the cytotoxicity of lapatinib through mediating FOXO3 deacetylation in both sensitive and resistant nasopharyngeal carcinoma (NPC) cells." (PMID 32372224, 2020).
osteoporosis (4 papers, 2021 to 2025). A condition of reduced bone mass, with decreased cortical thickness and a decrease in the number and size of the trabeculae of cancellous bone (but normal chemical composition), resulting in increased fracture incidence. "For example, increased hepatic SIRT2 expression promotes osteoporosis in aged mice and humans, while SIRT2 deficiency reduces bone resorption by upregulating LRG1 in sEVs, with LRG1 levels positively correlated with bone density." (PMID 40678144, 2025). "The μ-CT analysis showed that aged SIRT2-KOlyz mice (18 months old) of both sexes exhibited similar bone loss and osteoporosis compared to aged LoxP mice." (PMID 37188819, 2023). "The liver-specific SIRT2 deficiency (SIRT2-KOhep) abolishes bone loss and osteoporosis in aged mice and an ovariectomy (OVX)-induced postmenopausal osteoporosis mouse model." (PMID 37188819, 2023). "In sum, these results provide evidence that SIRT2-KOhep prevents aging-associated osteoporosis by suppressing osteoclastogenesis." (PMID 37188819, 2023). "Liver-specific SIRT2 deficiency inhibits osteoclastogenesis and alleviates bone loss in mouse models of osteoporosis." (PMID 37188819, 2023). "To investigate the molecular mechanisms underlying liver–bone communication by SIRT2 in senile osteoporosis, we first verified the effect of plasma from two aged mouse groups on osteoblast and osteoclast differentiation." (PMID 37188819, 2023). "Compared to young mice, SIRT2 protein expression was obviously increased in hepatocytes of both aged female and male mice with osteoporosis." (PMID 37188819, 2023). "Here, we uncovered hepatocyte–osteoclast communication regulated by SIRT2 with therapeutic potential in osteoporosis." (PMID 37188819, 2023). "We continued to verify the connection between LRG1 in sEVs (sEV-LRG1) and the protective role of SIRT2-KOhep in osteoporosis." (PMID 37188819, 2023). "Thus, pharmacological inhibition of hepatocyte SIRT2 is a promising approach that should be effective for the prevention and treatment of osteoporosis." (PMID 37188819, 2023). "In the present study, we mainly focused on the function of hepatic SIRT2 in osteoporosis, therefore the liver-specific knockout mice and AAV8 viral expression system with hepatocyte-specific TBG promoter were used to exclude the influence of SIRT2 in other organs." (PMID 37188819, 2023). "Therefore, our data provide definitive evidence that targeting hepatic SIRT2 or sEV-LRG1 is a powerful strategy for primary osteoporosis therapy." (PMID 37188819, 2023). "Given the protective role of SIRT2-KOhep in both aging-associated and OVX-induced osteoporosis, we evaluated whether AGK2, a specific SIRT2 inhibitor, can be repositioned for prevention or treatment of osteoporosis." (PMID 37188819, 2023). "Notably, treatment with AGK2 or LRG1-sEVs conferred a therapeutic benefit in osteoporosis, including in animal models and human primary cell cultures, corroborating targeting hepatocyte SIRT2 or sEV-LRG1 as a promising therapeutic modality in primary osteoporosis." (PMID 37188819, 2023). "Furthermore, we observed whether SIRT2 in BMDMs plays a role in osteoporosis." (PMID 37188819, 2023). "In the present study, the specific inhibitor of SIRT2, AGK2 was verified as a promising therapeutic agent for osteoporosis in OVX mice." (PMID 37188819, 2023). "The inter-organ action of SIRT2–sEV-LRG1–NF-κB–NFATc1 axis may also be essential to maintaining bone homeostasis and a promising therapeutic target in primary osteoporosis." (PMID 37188819, 2023). "Taken together, these data suggest that the hepatocyte SIRT2-regulated liver–bone axis, not BMDM-intrinsic SIRT2, is the predominant regulator of osteoclastogenesis and osteoporosis." (PMID 37188819, 2023). "In addition, using BMDM-specific SIRT2 knockout mice, we identified that the hepatocyte SIRT2-regulated liver–bone axis, not BMDM-intrinsic SIRT2, is the predominant regulator of osteoclastogenesis and osteoporosis." (PMID 37188819, 2023).